LINC01857 (long independently transcribed non-coding RNA 1857)
Synonyms: AC079767.4
Gene: Long non-coding RNA gene on chromosome 2 (207,662,371 to 207,679,122, forward strand). Ensembl gene ENSG00000224137.
Diseases named in the same sentence as LINC01857 in open-access papers:
LINC01857 is named in the same sentence as 12 diseases in open-access papers, as found by Europe PMC text mining. Sharing a sentence is not in itself a finding about the gene and the disease. The quoted sentences say what the papers report.
breast carcinoma (7 papers, 2021 to 2022). "For example, by interacting with CREBBP to promote the transcription of H3K27Ac and CREB1, LINC01857 promote the progression of breast cancer." (PMID 34425868, 2021). "LINC01857 is thought to promote breast cancer progression by regulating CREB1 activation via interacting with CREBBP." (PMID 34458145, 2021). "As it was recently reported, LINC01857 overexpression was observed in individuals with breast cancer, resulting in aggrandized cell expansion, aggressiveness, poor clinical aftermath and continuous apoptosis." (PMID 34793477, 2021). "Similarly, LINC01857 has been revealed to promote progression in cancers, such as glioma, B-cell lymphoma, and breast cancer, and predict the poor prognosis of breast cancer patients." (PMID 35741856, 2022). "For instance, LINC01857 acts as a tumor promotor in breast cancer by sponging miR-1281 to encourage cell biological behaviors, suggesting that LINC01857 could function as a ceRNA to competitively bind to a miR and become involved in cancers." (PMID 34793477, 2021). "LINC01857 is involved in gastric cancer, glioma, diffuse large B-cell lymphoma (DLBCL), hepatocellular carcinoma (HCC), and breast cancer (BC)." (PMID 36168326, 2022). "At present, there are still no reports about LINC01857 in malignant melanoma, and three reports indicating that LINC01857 was a potential oncogene in glioma, breast cancer 41 and pancreatic cancer." (PMID 34159752, 2021).
glioma (7 papers, 2021 to 2025). A benign or malignant brain and spinal cord tumor that arises from glial cells (astrocytes, oligodendrocytes, ependymal cells). "Upregulation of LINC01857 was reported in glioma cell lines and was shown to induce glioma cell proliferation, migration, and invasion." (PMID 36139694, 2022). "LINC01857 protein levels were elevated in glioma tissues compared to normal tissues and correlated with glioma grade." (PMID 36139694, 2022). "LINC01857 also functions as a sponge for miR-1281, which expression is decreased in glioma tissues." (PMID 36139694, 2022). "Therefore, LINC01857 is believed to promote glioma progression and tumor growth via regulation of the miR-1281/TRIM65 axis." (PMID 36139694, 2022). "Additionally, it has also been suggested that LINC01857 may promote tumorigenesis and progression through ceRNA-related mechanisms in diffuse large B-cell lymphoma, glioma, and gastric cancer." (PMID 34458145, 2021). "For example, LINC01857 sponges miR-1281 to promote TRIM65 expression and thus facilitates the development of glioma." (PMID 34425868, 2021). "LINC01857 acts as an oncogene that promotes BC development by promoting H3K27Ac and CREB1 transcription, regulates glioma progression by modulating the miR-1281/TRIM65 pathway, promotes the proliferation of cancer cells by activating the PI3K/mTOR pathway, and facilitates the EMT process in DLBCL." (PMID 36168326, 2022).
gastric cancer (5 papers, 2021 to 2023). A primary or metastatic malignant neoplasm involving the stomach. "It is associated with metastasis and poor prognosis in gastric cancer, and overexpression of LINC01857 in HCC promotes cell proliferation by regulating AGR2 and upregulating the AKT and ERK pathways." (PMID 36168326, 2022). "LINC01857 is also confirmed to be upregulated in gastric cancer tissues and related to lymph node metastasis and unfavorable outcome of patients with gastric cancer." (PMID 35662010, 2022). "A recent study revealed that LINC01857 promotes the migration and invasion of gastric cancer cells by regulating microRNA-200b." (PMID 34425868, 2021). "Likewise, studies have also indicated that LINC01857 regulates the penetration of immune cells like macrophages and Tregs in stomach cancer." (PMID 38054797, 2023).
diffuse large B-cell lymphoma (4 papers, 2021 to 2022). "For example, LINC01857 levels were increased within diffuse large B-cell lymphoma (DLBCL) tissues and cells." (PMID 36046633, 2022).
hepatocellular carcinoma (2 papers, 2021 to 2022). A malignant tumor that arises from hepatocytes. "LINC01857 has been reported to predict prognosis in hepatocellular carcinoma patients with fibrosis." (PMID 34425868, 2021).
pancreatic cancer (2 papers, 2021 to 2022). "Additionally, the authors will study the expression of LINC01857 in the serum of pancreatic cancer patients and investigate whether the serum expression level of LINC01857 can be used to distinguish between chemoresistant patients and chemosensitive patients with PDAC in the future." (PMID 35662010, 2022). "A subcellular fraction assay was done to ascertain the location of LINC01857 in PANC-1 and BxPC-3 human pancreatic cancer cells." (PMID 35662010, 2022). "In summary, these results elucidated that LINC01857 downregulation restrains cell proliferation, migration, invasion, and EMT process in pancreatic carcinoma." (PMID 35662010, 2022).
malignant melanoma (1 paper, 2021). "LINC02446, LINC01857, and LINC02384 may stimulate melanoma progression by reducing tumor‐protecting miR.891a.5p and miR.203b.3p." (PMID 34159752, 2021).
cancer (6 papers, 2021 to 2022). A tumor composed of atypical neoplastic, often pleomorphic cells that invade other tissues. "To date, as a novelty identified lncRNA, LINC01857 has been suggested to promote the malignant development of several cancers." (PMID 35662010, 2022). "Emerging evidence has demonstrated that LINC01857 exerts a pivotal function in many cancers." (PMID 35662010, 2022). "Several bioinformatics studies also confirmed the prognostic role of LINC01857 in cancer." (PMID 36168326, 2022). "LINC01857, as a pro-cancer factor, has been confirmed related to the development of many cancers." (PMID 36046633, 2022). "LINC01857 overexpression results in induced lymph node metastasis, cancer cell viability, frustrating clinical outcomes and tumor growth and inhibits apoptosis in human cancers, including gastric cancer and pancreatic ductal adenocarcinoma." (PMID 34793477, 2021). "Additionally, CCDC144NL-AS1 and LINC01857 have been experimentally studied in cancers." (PMID 35741856, 2022).
tumor (4 papers, 2021 to 2022). "In vivo studies showed that down-regulation of LINC01857 notably suppressed tumor growth and angiogenesis in nude mice." (PMID 36046633, 2022). "In addition, we revealed that LINC01857, LINC02446, and LINC02384, as competing endogenous RNAs (ceRNAs) of IL2RA and IL7R, were oncogenes, while miR‐203b‐3p and miR‐891a‐5p, as microRNA sponges of IL2RA and IL7R, respectively, act as potential tumor suppressor molecules." (PMID 34159752, 2021).
LINC01857 also shares sentences with these, for which no sentence is quoted: B-cell lymphoma (1 paper); pancreatic adenocarcinoma (1); stomach cancer (1).